REG4 (regenerating family member 4)
Description:
Calcium-independent lectin displaying mannose-binding specificity and able to maintain carbohydrate recognition activity in an acidic environment. May be involved in inflammatory and metaplastic responses of the gastrointestinal epithelium.
Synonyms: GISP; RELP; REG-IV
Tractability: Small molecule: it has a high-quality binding pocket. Antibody: UniProt places it where antibodies can reach, with high confidence; UniProt predicts a signal peptide or a membrane-spanning region; its Gene Ontology location is reachable by antibodies, with medium confidence.
Gene: Protein-coding gene on chromosome 1 (119,794,017 to 119,811,580, reverse strand). Ensembl gene ENSG00000134193.
Subcellular location: Secreted
Gene Ontology:
Molecular function: calcium ion binding; heparin binding; mannan binding; carbohydrate binding
Cellular component: cytoplasm; extracellular region
Genetic constraint (gnomAD): Loss-of-function variants: 17 observed, 23.73 expected, observed/expected ratio (o/e) 0.72, 90% interval 0.49 to 1.07. The upper end of that interval is the gene's LOEUF score, 1.07, which puts it in group 4 of 6, group 1 being the genes least tolerant of losing a copy. Missense variants: 194 observed, 174.98 expected, observed/expected ratio (o/e) 1.11, 90% interval 0.99 to 1.25. Synonymous variants: 61 observed, 60.31 expected, observed/expected ratio (o/e) 1.01, 90% interval 0.82 to 1.25.
Homologues: Orthologues: chimpanzee REG4 (99% identical), macaque REG4 (92% identical), pig REG4 (75% identical), rat Reg4 (66% identical), mouse Reg4 (66% identical), guinea pig REG4 (63% identical), rabbit REG4 (63% identical), tropical clawed frog MGC64513 (48% identical), tropical clawed frog reg4 (47% identical), tropical clawed frog reg1b (36% identical), Caenorhabditis elegans clec-150 (22% identical). Paralogues in human: REG3A (34% identical), REG3G (34% identical), REG1B (33% identical), REG1A (32% identical), CLEC19A (26% identical).
Diseases named in the same sentence as REG4 in open-access papers:
REG4 is named in the same sentence as 98 diseases in open-access papers, as found by Europe PMC text mining. Sharing a sentence is not in itself a finding about the gene and the disease. The quoted sentences say what the papers report.
gastric cancer (36 papers, 2009 to 2024). A primary or metastatic malignant neoplasm involving the stomach. "REG4 antibody significantly inhibited proliferation and chemosensitivity of gastric cancer cells to 5-FU and REG4 silencing caused the loss of stemness properties." (PMID 36172286, 2022). "Mouse models have demonstrated Reg4 to promote gastric cancer adhesion to murine peritoneum in vivo and a patient cohort associated Reg4 levels of peritoneal washings with peritoneal micro-metastasis." (PMID 33659040, 2021). "The REG protein family is also known to be associated with gastric cancer development and Reg1α and Reg4 have been suggested as prognostic markers for advanced stomach cancers in man." (PMID 23899160, 2013). "REG4 has been reported to be a marker for peritoneal metastasis in gastric cancer and this was supported by our study which showed that REG4 overexpression is associated with metastatic disease." (PMID 21092330, 2010). "Furthermore, tumour-associated neutrophils (TANs)-derived regenerating family member 4 (REG4) upregulates SRGN expression by activating cAMP-responsive element binding protein 1 (CREB1) in gastric cancer cells." (PMID 38862740, 2024). "Interestingly, in prostate cancer, Reg4 has been shown to be an independent predictor of relapse after prostatectomy and in gastric cancer associated significantly with tumor invasion depth, lymph node metastasis, and increased mortality." (PMID 33659040, 2021). "Similarly, relevant studies showed that REG4 mRNA level in peritoneal washes of gastric cancer patients is closely associated with gastric wall penetration and that REG4 is an independent prognostic factor for peritoneal recurrence-free survival." (PMID 27036049, 2016). "Elevated serum concentration of REG4 in carcinoma patients compared to those in healthy controls has been a finding in pancreatic cancer, gastric cancer and gallbladder cancer, indicating that serum REG4 could serve as a diagnostic biomarker." (PMID 25295732, 2014). "In addition, several transcription factors downstream of EGFR are closely associated to poor outcome of gastric cancer patients, which might contribute to REG4 inducement after EGFR ligands stimulation." (PMID 27036049, 2016). "Collectively, these results suggest that TANs-derived REG4 upregulates SRGN in gastric cancer cells." (PMID 38862740, 2024). "Another report described how REG4 promoted proliferation, tumor growth, and migration of gastric cancer cells through the protein kinase B pathway." (PMID 36172286, 2022). "In gastric cancer cells, REG4 enhanced the resistance of gastric cancer cells to 5-FU through the mitogen-activated protein kinase/extracellular-signal-regulated kinase/Bim pathway." (PMID 36172286, 2022). "Meanwhile, REG4 expression was significantly associated with both the intestinal mucin phenotype (mucin 2 [MUC2] and CDX2) and neuroendocrine differentiation of gastric cancer." (PMID 36172286, 2022). "At the mRNA level, REG4 gene was significantly up-regulated in gastric cancer compared with normal mucosa, while our group showed higher REG4 expression in intestinal metaplasia than in gastritis and gastric cancer." (PMID 36172286, 2022). "GPR37 is identified to be in the same complex of REG4 (regenerating islet-derived family, member 4) and mediates REG4’s signal transduction, promoting peritoneal metastasis of gastric cancer cell." (PMID 36430912, 2022). "It was suggested that REG4 overexpression predicted chemoresistance in gastric cancer cells, possibly by promoting proliferation and stemness." (PMID 36172286, 2022). "In gastric cancers, serum REG4 levels were found to be significantly higher than those in healthy individuals." (PMID 34577861, 2021). "In gastric cancer, in vitro Reg4 antibody has inhibited gastric cancer proliferation and enhanced the apoptotic effect of 5-FU." (PMID 33659040, 2021).
gastric cancer (continued). "Antibody against REG4 significantly inhibited proliferation in gastric cancer cells (MKN45 and AGS) and synergistically enhanced the lethal effect of 5-FU via the MAPK/ERK/Bim pathway." (PMID 33489872, 2020). "Another study revealed that miR-24 directly downregulated REG4 expression by binding its 3′ untranslated region and restrained gastric cancer progression." (PMID 33489872, 2020). "Signet ring cell carcinoma, an aggressive phenotype of gastric cancer, expressed more REG4 than other types of gastric cancer." (PMID 33489872, 2020). "REG4 expression in gastric cancer positively correlates with the cell invasive depth, clinical stages, diffuse type, poor differentiation, distant metastasis and intrinsic drug resistance to 5-FU." (PMID 33489872, 2020). "REG4 purportedly interacts with the G-coupled receptor 37 (GPR37) in gastric cancer cells to promote metastasis." (PMID 31696115, 2019). "REG4 also phosphorylates AKT in addition to EGFR in gastric cancer cells resulting in the increased expression of anti-apoptotic BCL-2, BCL-XL and BIRC5." (PMID 31696115, 2019). "REG4 is thought to be an early stage serum biomarker of gastric cancer metastasis and resistance to apoptosis after treatment with 5-fluorouracil (5-FU) used for chemotherapy." (PMID 31696115, 2019). "REG4 is overexpressed in colorectal and gastric carcinomas whereas REG3A is expressed in hepatocellular carcinomas with β-catenin mutations." (PMID 31696115, 2019). "REG4 has been shown to enhance metastasis in gastric carcinomas and also contributes to invasiveness in pancreatic and colorectal carcinoma." (PMID 31303963, 2019). "The present study shows that REG4 promotes peritoneal metastasis of gastric cancer through G-protein coupled receptor 37 (GPR37), and triggers a positive feedback loop." (PMID 27036049, 2016). "In the present study, we show that high expression of REG4 correlates with advanced stage and poor survival prognosis for gastric cancer patients." (PMID 27036049, 2016). "In conclusion, REG4 promotes peritoneal metastasis of gastric cancer through GPR37 and triggers a positive feedback loop." (PMID 27036049, 2016). "It revealed that 57 out of 102 (55.9%) gastric cancer tissues were REG4 positive, predominantly located in the cytoplasm, however occasionally weak or no staining was observed in non-neoplastic tissues (p<0.01)." (PMID 27036049, 2016). "Our results from tissue array showed that REG4 is significantly over expressed in gastric cancer tissues, confirming previous studies on REG4 expression in gastric cancer and colorectal cancer." (PMID 27036049, 2016). "qRT-PCR and Western blot showed that REG4, on both mRNA and protein level, was relatively more abundant in gastric cancer celllines and was dramatically upregulated in SNU-16." (PMID 27036049, 2016). "Our results showed that REG4 was more abundantly expressed in gastric cancer cells and its level varied among different cell lines." (PMID 27036049, 2016). "These in vitro and in vivo experiments suggest that REG4 promotes peritoneal metastasis of gastric cancer cells by increasing adhesion ability." (PMID 27036049, 2016). "Then we knocked down GPR37 in REG4 overexpressed cell lines or rhREG4 stimulated cells to test their effects upon the biological behaviors of gastric cancer cells." (PMID 27036049, 2016). "We first examined REG4 expression in 9 gastric cancer celllines and 1 immortalized gastric epithelial cellline." (PMID 27036049, 2016). "It seems that REG4 expression is enhanced transcriptionally in gastric cancer cells, so we scanned the REG4 promoter for potential transcription factors." (PMID 27036049, 2016). "In the present study, we demonstrate that REG4 is able to promote peritoneal metastasis of gastric cancer through GPR37 by enhancing adhesion ability." (PMID 27036049, 2016).
gastric cancer (continued). "We have reported that REG4 is significantly over-expressed in gastric cancer tissues(especially in signet-ring cell carcinoma) than in corresponding normal tissues, and high expression of REG4 is positively related to lymph node metastasis." (PMID 27036049, 2016). "We next analyzed the correlation between REG4 expression and the clinicopathological status of gastric cancer patients." (PMID 27036049, 2016). "REG4 mRNA expression levels in surgically resected specimens and the peritoneal wash were closely related to those in wall-penetrating gastric carcinoma." (PMID 26077911, 2015). "Gene Set Enrichment Analysis (GSEA) conducted on the commonly downregulated genes in responder models revealed a specific signature shared with other gastrointestinal tumors, such as cholangiocarcinoma, gastric cancer and colorectal adenoma, with REG4 identified as a hub gene." (PMID 39632825, 2024). "The expression of the intestinal mucosal markers MUC13, TFF3, SPINK4, FABP1, and REG4 were increased in the GC type 1 subclass, while, the expression of the previously identified gastric cancer marker gene KRT7 was increased significantly in the GC type 2 subclass." (PMID 35785171, 2022). "Additionally, SRY-box transcription factor 9 (SOX9) knockdown upregulated REG4 protein expression in gastric cancer cells; a positive correlation of REG4 expression with SOX9 expression in gastric cancer was noted." (PMID 36172286, 2022). "REG4 mRNA was found to positively correlate with the wall penetration, depth of invasion, and clinicopathological stages of gastric cancer." (PMID 36172286, 2022). "In gastric cancer-initiating cells, upregulation of REG4 has been identified." (PMID 34577861, 2021). "Among the top 10 DRGs for Chinese (GSE54129), six genes have been reported to be gastric cancer (GC) related (REG4, ANXA13, C7, ASS1, MSMB, CREB1) and the rest four were directly regulated by known gastric cancer genes in our GRNs, in which two genes are also cancer related (BPTF, CLCA1)." (PMID 29745833, 2018). "Also, G protein-coupled receptor 37 (GPR37) is identified to be in the same complex of REG4, which mediates REG4′s signal transduction and promotes peritoneal metastasis of gastric cancer cell." (PMID 27036049, 2016). "Since adhesion to peritoneum is the prerequisite for peritoneal metastasis, we went on to evaluate the effect of REG4 on the adhesive behavior of gastric cancer cells by performing adhesion assays on plates coated with different extracellular matrix components." (PMID 27036049, 2016). "Again, this is consistent with our previous findings in gastric cancer, which showed positive REG4 expression in signet ring cells, and mucinous carcinoma, and higher expression in well- and moderately-differentiated adenocarcinoma than poorly-differentiated adenocarcinoma." (PMID 26077911, 2015). "Moreover, REG4, a member of the C-type lectin superfamily, was reported to be a potential prognostic indicator for the evaluation of the survival time of gastric cancer patients." (PMID 25504222, 2014). "According to a recent report, regenerating islet-derived protein 4 (REG4), a member of the C-type lectin superfamily, may be a good serum marker for the early diagnosis of gastric cancer." (PMID 25504222, 2014). "Increased REG4 IHC expression has been suggested as a marker of poor prognosis in gastric cancer, and elevated tissue levels of REG4 mRNA may be a marker of poor prognosis in CRC." (PMID 25295732, 2014). "Moreover, we fond REG4, a gene known to be up-regulated in gastric cancer." (PMID 37917660, 2023). "In addition, to simulate in vivo circumstances, we also examined adhesive ability to murine peritoneum, and such adhesion assays further confirmed that REG4, indeed, could enhance adhesive ability of gastric cancer cells." (PMID 27036049, 2016).
gastric cancer (continued). "As for molecular mechanisms, REG4 expression facilitated invasion and migration of gastric cancer cells by up-regulating SOX9 expression, in contrast to REG4 knockdown." (PMID 36172286, 2022). "In diffuse-type gastric carcinoma cells, TGF-β signaling inhibits REG4 expression in the cancer-initiating cells." (PMID 31696115, 2019). "The seven RNAs upregulated in gastric cancer were CLDN18, EPCAM, REG4, BBC3, OLFM4, PPARG, and CDH17, while the two downregulated genes were IFITM1 and HIF1A." (PMID 22929309, 2012). "All 14 REG4-positive patients with gastric cancer showed no change or disease progression when treated with a combination of low-dose 5-FU and cisplatin." (PMID 36172286, 2022). "In gastric cancer lines, SiRNA knockdown of Reg4 promoted 5-FU induced apoptosis with no change in 5-FU metabolites inferring a novel resistance pathway." (PMID 33659040, 2021). "In mammalian cells, caudal type homeobox 2 (CDX2) was found to induce REG4 expression by binding to consensus CDX2-binding elements upstream of the REG4 gene, supported by the positive relationship between CDX2 and REG4 expression in gastric cancer cells and tissues." (PMID 36172286, 2022). "Moreover, REG4 positivity in metastasized human gastric cancer was significantly higher than that in negative cases." (PMID 33489872, 2020). "Additionally, REG4 may be a better serum marker than carbohydrate antigen 19-9 (CA199) and carcinoembryonic antigen (CEA) for early diagnosis and as a prognostic indicator of gastric cancer." (PMID 33489872, 2020).
colorectal cancer (21 papers, 2013 to 2025). A primary or metastatic malignant neoplasm that affects the colon or rectum. "In conclusion, we have shown that particularly the combination of REG4 with A1AT in tumors associate with CAT in patients with colorectal cancer." (PMID 38066386, 2024). "This nested case–control study shows that combined protein expression of A1AT and REG4 associate with CAT in patients with colorectal cancer." (PMID 38066386, 2024). "The region of gain of chromosome 1p included the colorectal cancer-associated genes REG4 and NOTCH2 and gain of 15q included the genes MAP2K1, SMAD3, SMAD6, and IGF1R, among others." (PMID 31620944, 2019). "Interestingly, REG4 expression was recently shown to be induced by KRAS mutation in colorectal cancer cells, and act as a driver of K-RAS-induced tumorigenic effects." (PMID 38066386, 2024). "Association between REG4 expression and clinicopathologic parameters in colorectal cancer." (PMID 25295732, 2014). "In colorectal cancer, Reg4 expression, regulated by the transcription factor SP1, played an important role in triggering the EGFR/Akt/AP-1 signaling pathway." (PMID 39857608, 2024). "We recently identified an RNA-sequencing profile that associates with CAT in colorectal cancer (CRC) patients, with REG4, SPINK4, and SERPINA1 as the top-3 upregulated genes at mRNA level." (PMID 38066386, 2024). "Statistically, REG4 mRNA was more expressed in colorectal cancers (especially mucinous carcinomas) than in normal colorectal mucosa." (PMID 36172286, 2022). "Statistically, REG4 expression was significantly lower in colorectal cancer than in normal mucosa or adenomas, and inversely correlated with poor differentiation, venous invasion, low expression of MUC2 and EGFR phosphorylated at Tyr1068." (PMID 36172286, 2022). "In an organoid model, mutant KRAS-induced REG4 promoted colorectal cancer stemness via a Wnt/β-catenin pathway." (PMID 36172286, 2022). "In radiochemotherapy (RCT)-sensitive colorectal cancer cells, REG4 expression was down-regulated, while it was increased in radiochemoresistant cells." (PMID 36172286, 2022). "Background and objectives: The present study aimed to evaluate the clinicopathological significance and prognostic implications of REG4 immunohistochemical expression in colorectal cancer (CRC)." (PMID 34577861, 2021). "This correlated expression of Reg4, CD44 and CD44ICD establishes an important axis of Reg4-CD44-CD44ICD, a hallmark suggesting a crucial role in colorectal cancer biology." (PMID 33659040, 2021). "This study aimed to evaluate the clinicopathological significance of REG4 expression in colorectal cancer (CRC) using immunohistochemistry." (PMID 34577861, 2021). "Whereas, studies have suggested that REG4 can promote colorectal cancer cell proliferation and elevate resistance to drug-induced apoptosis, in vivo and in vitro." (PMID 33489872, 2020). "REG4 treatment accelerates G1/S and G2/M phase transition, coupled with increased mitotic index of colorectal cancer cells." (PMID 33489872, 2020). "Notably, REG4 promoted migration and invasion of colorectal cancer cells via its carbohydrate-recognition domain in both autocrine and paracrine manners, which was significantly decreased by anti-REG4 antibody." (PMID 36172286, 2022). "REG4 was obviously upregulated in colorectal cancer (CRC) tissue compared to the normal tissue." (PMID 35928108, 2022). "Further study showed that REG4 expression was associated with lymph node metastasis, distant metastasis, metastatic recurrence in the liver, advanced TNM stage, histologic grade, and MMP-7 expression in colorectal cancer." (PMID 36172286, 2022). "In addition, compared with normal colorectal tissues, REG4 gene expression was observed to have increased in colorectal cancer tissues." (PMID 34577861, 2021).